NCS1 (neuronal calcium sensor 1)
Diseases named in the same sentence as NCS1 in open-access papers (continued):
Sharing a sentence is not in itself a finding about the gene and the disease.
prostate carcinoma (2 papers, 2018 to 2023). A carcinoma that arises from epithelial cells of the prostate gland. "Agents that interfere with the NCS1-dependent pathway may offer protection from changes in neurological functions in patients with a variety of cancers, including breast, ovarian, lung, and prostate cancers." (PMID 29484113, 2018).
Achalasia (1 paper, 2016). A disorder of esophageal motility characterized by the inability of the lower esophageal sphincter to relax during swallowing and by inadequate or lacking peristalsis in the lower half of the body of the esophagus. "We observed a number of sequences involving the calcium signaling pathway (ie, CACNA1C, CACNB2, KCNMA1, CHRM2, CAV1, and NCS1) that were differentially expressed and were able to characterize these genes into possible functions related to achalasia pathogenesis." (PMID 27511445, 2016).
Adrenocortical Cancer (1 paper, 2023). "NCS1 was positively correlated with microsatellite instability in BRCA, DLBC, UCS, ACC (Adrenocortical Cancer), LUSC, TGCT, and LIHC and negatively correlated with expression in KICH, THCA, and STAD." (PMID 37893139, 2023).
Breast invasive carcinoma (1 paper, 2023). "High expression of NCS1 was detected by immune histochemical staining in LIHC (Liver hepatocellular carcinoma), BRCA (Breast invasive carcinoma), KIRC (Kidney renal clear cell carcinoma), and SKCM (Skin Cutaneous Melanoma)." (PMID 37893139, 2023).
cervical cancer (1 paper, 2023). A primary or metastatic malignant neoplasm involving the cervix. "NCS1 was not expressed in CESC (Cervical Cancer), LUAD (Lung Adenocarcinoma), PCPG (Pheochromocytoma & Paraganglioma), and in MESO (Mesothelioma), SARC (Sarcoma), and UVM (Ocular melanomas) due to some missing data, and the results could not be derived." (PMID 37893139, 2023).
cryptococcosis (1 paper, 2020). An acute or chronic, localized or disseminated infection by Cryptococcus neoformans. "To determine whether disruption of Ncs1-mediated calcium homeostasis also contributes to pathogenicity, we compared the virulence of the ncs1Δ mutant strain to that observed for the WT and ncs1Δ::NCS1 strains in a mouse inhalation model of cryptococcosis." (PMID 32907953, 2020).
dementia (1 paper, 2023). Loss of intellectual abilities interfering with an individual's social and occupational functions. "Further, we identified ACTA2, LTBP2, and NCS1 as potential contributors to dementia risk." (PMID 38016990, 2023).
glioma (1 paper, 2023). A benign or malignant brain and spinal cord tumor that arises from glial cells (astrocytes, oligodendrocytes, ependymal cells). "Research has demonstrated that NCS1 overexpression promotes invasion and proliferation in various cancers, such as prostate, breast, glioma, ovarian, and hematologic malignancies." (PMID 37893139, 2023).
Hyperammonemia (1 paper, 2022). An increased concentration of ammonia in the blood. "In this work, using the methods of fluorescence microscopy, vitality tests, immunocytochemistry, and PCR analysis, the molecular mechanisms of the protective action of NCS-1 in ischemia/reoxygenation and hyperammonemia were established." (PMID 36555318, 2022). "The mass death of NCS-1-KD cells during OGD and hyperammonemia has been associated with the induction of a more pronounced network hyperexcitation symptom, especially in the population of GABAergic neurons, leading to a global increase in cytosolic calcium ([Ca2+]i)." (PMID 36555318, 2022). "Thus, NCS-1-KD contributed to the formation of hyperexcitation of the neuronal network during ischemia and hyperammonemia, leading to damage primarily to GABAergic neurons due to the switching of high-amplitude Ca2+-oscillations into a global irreversible increase in [Ca2+]i." (PMID 36555318, 2022).
Insulin resistance (1 paper, 2019). Increased resistance towards insulin, that is, diminished effectiveness of insulin in reducing blood glucose levels. "Since obesity-linked insulin resistance may be associated with dysfunctional adipocytes, we concentrated on adipocytes for further analysis of the NCS-1−/− phenotype." (PMID 31001084, 2019). "Thus, HFD-fed NCS-1−/− mice exhibit in comparison to WT littermates a significantly reduced IR expression, which may explain the pronounced insulin resistance observed especially with HFD-fed NCS-1−/− mice." (PMID 31001084, 2019).
insulinoma (1 paper, 2022). "Moreover, in rat insulinoma cells, the overexpression of NCS1 in wfs1KO cells was also shown to restore calcium homeostasis including ATP-evoked ER calcium release and resting cytosolic calcium." (PMID 36320410, 2022).
ischemia (1 paper, 2022). A hypoperfusion of the BLOOD through an organ or tissue caused by a PATHOLOGIC CONSTRICTION or obstruction of its BLOOD VESSELS, or an absence of BLOOD CIRCULATION. "However, we clearly established the role of NCS-1 in protecting GABAergic neurons, and, consequently, other neurons of the neuronal network from hyperexcitation, ischemia-like conditions, and reoxygenation." (PMID 36555318, 2022). "The role of NCS-1 in the protection of neurons and especially their individual populations from ischemia and hyperexcitation has not been practically studied." (PMID 36555318, 2022).
kidney inflammation (1 paper, 2021). "APOL1 variants interfere with autophagy by antagonizing Ca2+-dependent binding of APOL3 to neuronal calcium sensor 1 (NCS-1) and interacting with PI4-kinase IIIB in podocytes, which aggravates kidney inflammation." (PMID 34831428, 2021).
Lewy body disease (1 paper, 2023). "Based on DisGeNET, NCS1 and its related genes are primarily associated with phenotypes of Lewy body disease." (PMID 37893139, 2023).
lung carcinoma (1 paper, 2020). "As a member of the NCS family, neuronal calcium sensor 1 (NCS1) is a multifunctional protein with the ability to enhance the aggressiveness of lung cancer." (PMID 33046994, 2020).
Obesity (1 paper, 2019). Accumulation of substantial excess body fat. "Here we show that adult NCS-1−/− mice, especially when fed a high-fat diet (HFD), are hyperglycemic and hyperinsulinemic, typical symptoms associated with obesity." (PMID 31001084, 2019). "The results suggested that NCS-1−/− obesity most likely had other reasons than excessive feeding behavior and lack of physical activity." (PMID 31001084, 2019). "Though behavioral phenotypes of NCS-1−/− mice have been investigated extensively, their obesity, which represents the most apparent adult NCS-1−/− phenotype, remained uncharacterized so far." (PMID 31001084, 2019). "We wanted to know whether this also applies to obesity observed in NCS-1−/− mice." (PMID 31001084, 2019).
pancreatic cancer (1 paper, 2019). "Several other proteins in this group also displayed greater induction under serum-free conditions (NOL3, NCS1, CD151), suggesting synergistic effects of hypoxia and nutrient deprivation on pancreatic cancer cell development and angiogenic activity." (PMID 31666928, 2019).
retinoblastoma (1 paper, 2021). A malignant tumor that originates in the nuclear layer of the retina. "Retinoblastoma cells express not only NCS-1 but also recoverin, both of which form disulfide aggregates and may collectively affect proteasome capacity." (PMID 34830487, 2021). "To test this hypothesis, we used a model based on Y79 retinoblastoma cells showing prominent endogenous expression of NCS-1." (PMID 34830487, 2021).
Stroke (1 paper, 2025). Sudden impairment of blood flow to a part of the brain due to occlusion or rupture of an artery to the brain. "EA was found to down-regulate miR-191a-5p, which, in turn, targeted neuronal calcium sensor 1 (NCS-1), enhancing cell viability, reducing apoptosis, and improving neurological outcomes in rats post-stroke." (PMID 39974363, 2025).
cancer (13 papers, 2018 to 2025). A tumor composed of atypical neoplastic, often pleomorphic cells that invade other tissues. "For instance, HSPA12A is known to regulate inflammatory responses, ATP2C2 plays a critical role in immune microenvironment, and NCS1 is associated with immunotherapy and prognosis of cancer." (PMID 41140666, 2025). "Our study sheds light on the potential value of NCS1 in cancer prognosis and immunotherapy and contributes to a deeper understanding of the mechanisms underlying NCS1’s interaction with various immune cells in tumors." (PMID 37893139, 2023). "NCS1 has genomic mutations as well as aberrant DNA methylation in multiple cancers compared to normal tissues." (PMID 37893139, 2023). "NCS1 is involved in immune regulation and has the potential to become a pan-cancer diagnostic biomarker, exhibiting significant differences in various immune subtypes and molecular subtypes of tumors." (PMID 37893139, 2023). "For instance, NCS1 and CSF-1 are associated with promotion of tumor aggressiveness and poor outcome in various cancer types." (PMID 33671266, 2021). "Interestingly, NCS-1 silencing diminishes the susceptibility of Y79 cancer cells to oxidative stress-induced apoptosis, suggesting that NCS-1 may mediate redox-regulated pathways governing cell death/survival in response to oxidative conditions." (PMID 34830487, 2021). "Due to its high expression in cancer cells, NCS1 demonstrates a resistance profile against T cell dysfunction and immunosuppressive therapies, which can promote resistance to the killing effect induced by T cells during ICB treatment." (PMID 37893139, 2023). "This study employed machine learning, transcriptome mapping from The Cancer Genome Atlas (TCGA), and relational databases to assess the enriched expression pattern of NCS1 in different cancer subtypes." (PMID 37893139, 2023). "NCS1 demonstrates differential methylation across at least eight tumor types, making it a pan-cancer-wide differentially methylated CpG site capable of delineating distinct functional groups." (PMID 37893139, 2023). "Significant differences were obtained between NCS1 expression and pan-cancer in Stromal Score, tumor microenvironment score, immune score, and immune infiltration-related cells." (PMID 37893139, 2023). "As a regulator of immune escape in tumors, elevated expression of NCS1 in cancer cells leads to resistance against T-cell-mediated killing effects during immune checkpoint blockade (ICB) therapy." (PMID 37893139, 2023). "The findings revealed significant variations in immune cell enrichment among different NCS1 SCNAs in pan-cancer, indicating varying degrees of immune cell infiltration." (PMID 37893139, 2023). "It is suggested that the genomic alteration of NCS1 in pan-cancer is closely related to the degree of immune infiltration." (PMID 37893139, 2023). "We examined the correlation between NCS1 methylation levels and overall survival in patients with different cancer types, revealing its significant prognostic value in more than four cancer types." (PMID 37893139, 2023). "It is well known that APOL3-controlled NCS-1 promotes cancer cell motility, metastatic spread, and survival." (PMID 35919504, 2022). "Accordingly, the APOL3‐controlled NCS‐1 is known to promote motility, metastatic spread and survival of cancer cells, and the NCS‐1 antagonist CALN‐1 also exhibits relationship with metastatic cell migration." (PMID 32530132, 2021). "Our primary goal was to determine the specific extracellular conditions and intracellular signaling pathway(s) that lead to increased NCS1 expression in cancer cells." (PMID 32239615, 2020). "In the present study, we further validate the importance of NCS1 for cell survival and motility and provide evidence that NCS1 modulates signaling pathways important for cancer progression." (PMID 32239615, 2020).
cancer (continued). "With the evidence that there is a specific mechanism of NCS1 up‐regulation with stress, the question arises regarding the specific function of NCS1 in cancer cells, and which cellular signaling pathways are regulated by NCS1 to promote tumor aggressiveness." (PMID 32239615, 2020). "In conclusion, we describe a novel role for NCS1 as stress response protein linking the tumor microenvironment and cancer progression." (PMID 32239615, 2020). "In the context of cancer, NCS‐1 is a potential target for the prevention of paclitaxel‐induced peripheral neuropathy." (PMID 31647602, 2020). "NCS1 was found to have significant differences in different tumor stages of pan-cancer." (PMID 37893139, 2023). "This study lays the foundation for further research on the impact of NCS1 methylation on cancer." (PMID 37893139, 2023). "Moreover, they demonstrated that high NCS1 expression in cancer patients reduces their survival time and further confirmed the pro-cancer role of NCS1 through biological validation using immunohistochemical staining." (PMID 37893139, 2023). "The expression of NCS1 in 33 human cancers was determined using the TCGA and GTEx portals." (PMID 37893139, 2023). "Given that NCS1 plays a vital role in regulating immune tolerance and tumor development across various histological types in pan-cancer, we thought it might be routinely applied to various tumors." (PMID 37893139, 2023). "In addition, NCS-1 is aberrantly expressed in certain cancers, and the level of its expression correlates with tumor aggressiveness and patients’ survival rates." (PMID 34830487, 2021). "For this purpose, we explored whether NCS1 expression levels change in response to external stimuli in vitro and investigated the translational relevance of the identified signaling mechanism in human cancer." (PMID 32239615, 2020). "Although previous studies showed that high NCS1 expression leads to more aggressive behavior of tumor cells, specifically increased cell survival and motility and worse patient outcome, our observations are a first step toward understanding how high NCS1 levels become elevated in cancer cells." (PMID 32239615, 2020). "However, the role of NCS1 in immune infiltration and cancer prognosis is still unknown." (PMID 37893139, 2023). "Several proteins already known to promote tumor metastasis (NOTCH2, NCS1, NUSAP1, CD151), were increased more than 10-fold under hypoxic conditions, further demonstrating the potent effects of oxygen restriction on cancer cell biology." (PMID 31666928, 2019). "Furthermore, NCS-1 has a role as a survival factor through indirect activation of the PI3K signaling pathway, which is altered in some forms of cancer." (PMID 38564162, 2024). "NCS-1 is a calcium (Ca2+) sensor found in many tissues, primarily neurons, and TRPA1 is a Ca2+ channel involved not only in thermal and pain sensation but also in conditions such as cancer and chemotherapy-induced peripheral neuropathy, in which NCS-1 is also a regulatory component." (PMID 38564162, 2024).
tumor (8 papers, 2019 to 2023). "The study explored the correlation between NCS1 expression and tumor-infiltrating lymphocytes (TILs), as well as associated immune markers." (PMID 37893139, 2023). "Our findings revealed significant differences in immune infiltration-associated cells with respect to NCS1 expression across different tumor types." (PMID 37893139, 2023). "NCS1 overexpression also is linked to enhanced tumor load in mouse models, likely related to a NCS1-dependent enhancement of cell motility and invasion." (PMID 36206298, 2022). "However, the underlying mechanism by which NCS1 contributes to increased tumor aggressiveness has yet to be identified." (PMID 32239615, 2020). "The Neural Calcium Sensor1 (NCS1) is a crucial protein that binds to Ca2+ and is believed to play a role in regulating tumor invasion and cell proliferation." (PMID 37893139, 2023). "The discovery that NCS1 can reduce cross reactivity with other proteins and exhibits tumor-specific protein isoforms has stimulated fundamental mechanistic studies focused on NCS1." (PMID 37893139, 2023). "The findings revealed that high expression levels of NCS1 were associated with reduced overall survival (OS) and disease-free survival (DFS), indicating significant tumor heterogeneity." (PMID 37893139, 2023). "The impact of NCS1 on the tumor microenvironment (TME) immune mechanisms and immune response was investigated by analyzing the correlation between NCS1 expression and tumor mutation burden (TMB) as well as microsatellite instability (MSI)." (PMID 37893139, 2023). "NCS1 is a crucial calcium-binding protein believed to play a role in regulating tumor invasion and cell proliferation." (PMID 37893139, 2023). "In summary, our investigation encompassed NCS1 expression patterns, correlation with tumor immune infiltration and immune infiltrating cells, prognostic value, enrichment pathways, and potential targeting drugs from multiple perspectives." (PMID 37893139, 2023). "High NCS1 levels promote tumor aggressiveness by enhancing cell survival and migration in 2D and 3D cell culture models and in mice." (PMID 32239615, 2020). "The novel finding that extracellular stressors lead to NCS1 up‐regulation helps us understand how high NCS1 expression leads to more aggressive behavior of tumor cells and worse patient outcome." (PMID 32239615, 2020). "Many genes in these chromosome regions, such like ERLIN2 (amp 8p11.23), VAV2 (del 9q34.2), ADAMTS6 (del 5q12.3) and NCS1 (del 9q34.11), are known to be related with tumor invasion and metastasis." (PMID 33193655, 2020). "Overall, our study is the first to elucidate an underlying signaling mechanism through which the Ca2+‐binding protein NCS1 influences tumor aggressiveness and progression." (PMID 32239615, 2020). "This study investigates the underlying mechanism by which the calcium (Ca2+)‐binding protein NCS1 promotes increased tumor aggressiveness." (PMID 32239615, 2020). "In this study, we aimed to investigate the mechanisms by which NCS1 enhances tumor progression and aggressiveness." (PMID 32239615, 2020). "Neuronal calcium sensor 1 (NCS1) is a ubiquitously expressed Ca2+‐binding protein that promotes tumor aggressiveness by enhancing cell survival and metastasis." (PMID 32239615, 2020). "Whereas previous publications focused on the effect of NCS1 overexpression (NCS1 OE) on promoting tumor aggressiveness, here we investigate the effect of NCS1 KO on cell survival, migration, and proliferation." (PMID 32239615, 2020). "Furthermore, the stromal score, tumor microenvironment score, and immune score exhibited distinct expression patterns of NCS1 across various tumor types." (PMID 37893139, 2023). "A genetic screening technique based on the ICSDB database was used to investigate whether the NCS1 gene could increase T cell-mediated sensitivity and tumor cell resistance by interacting with 28 types of TILs." (PMID 37893139, 2023).